LTBP2 (latent transforming growth factor beta binding protein 2)
Diseases named in the same sentence as LTBP2 in open-access papers (continued):
Sharing a sentence is not in itself a finding about the gene and the disease.
gastric cancer (7 papers, 2019 to 2026). A primary or metastatic malignant neoplasm involving the stomach. "LTBP2, highly expressed in White race, was associated with migration and invasion of gastric cancer cells and predicts poor outcome of patients with gastric cancer." (PMID 34105890, 2021). "Previous studies have demonstrated that high expression of LTBP2 was associated with poor outcome and tumor progression in thyroid and gastric cancer." (PMID 35002722, 2021). "Kaplan‒Meier Plotter online website analysis of the LTBP2 gene and the prognosis of gastric cancer patients showed that the prognosis of patients with high LTBP2 expression was significantly lower than that of patients with low LTBP2 expression (P<0.01)." (PMID 38577985, 2024). "Analysis of the correlation between LTBP2 and the NF-κB2 gene using data from shared clinical samples of gastric cancer patients showed a significant positive correlation." (PMID 38577985, 2024). "Our data demonstrated that silencing LTBP2 induces ferroptosis via downregulation of the Nrf2 pathway in gastric cancer cells." (PMID 35968244, 2022). "In order to further verify the role of Nrf2 in LTBP2-regulated cell ferroptosis process, gastric cancer cells were cocultured with NK-252 (an Nrf2 activator), and changes in ferroptosis markers and proteins were detected." (PMID 35968244, 2022). "In this study, a series of experiments were conducted to investigate the role and explored the regulatory mechanism of LTBP2 in ferroptosis of gastric cancer cells." (PMID 35968244, 2022). "Since the main inducer of ferroptosis is lipid peroxidation, we investigated whether LTBP2 affects the levels of lipid peroxidation in gastric cancer cells." (PMID 35968244, 2022). "Moreover, knockdown of LTBP2 inhibited the proliferation and invasion in thyroid carcinoma and gastric cancer cells." (PMID 35002722, 2021). "Gastric cancer (GC) often develops resistance to cisplatin treatment, but while latent transforming growth factor β-binding protein (LTBP2) is recognized as a potential regulator in GC, its specific role in cisplatin resistance is not fully understood." (PMID 38577985, 2024). "Gastric cancer cell lines AGS, BGC-823, MKN-28, and MGC-803 were transfected with LTBP2 siRNA-3 or control siRNA, respectively." (PMID 35968244, 2022). "ROS levels in gastric cancer cells (AGS and MKN-28) were detected and the results showed a significant increase in ROS levels in the LTBP2-SiRNA group compared with the control group." (PMID 35968244, 2022). "However, the role of LTBP2 in gastric cancer and its regulation of ferroptosis remain unknown." (PMID 35968244, 2022). "However, the results showed that the apoptosis rate of gastric cancer cells (AGS and MKN-28) did not change significantly after transfection with LTBP2." (PMID 35968244, 2022).
heart failure (7 papers, 2018 to 2026). Inability of the heart to pump blood at an adequate rate to meet tissue metabolic requirements. "Compared with LTBP2 and OGN, PTN exhibited enrichment in myocardial infarction, which is the primary cause of cardiac ischemia and subsequent heart failure." (PMID 39722892, 2024). "Notably, within HLHS fibroblasts, we find increased expression of LTBP2 (previously implicated in TGF β signaling, enriched in activated fibroblasts in adult heart failure, and is a serum biomarker for RV failure in pulmonary arterial hypertension patients)." (PMID 40502733, 2025). "The results showed that, compared to normal samples, HMGN2, HTRA1, LTBP2, and MFAP4 were significantly upregulated in heart failure, while MYH6 was downregulated (p < 0.001)." (PMID 40406620, 2025). "Latent transforming growth factor beta binding protein 2 (Ltbp2; upregulated in MCT RV: protein = 2.67-fold, transcript = 4.16-fold) is involved in the regulation of TGF-β and is significantly elevated in the LV from heart failure patients." (PMID 36388115, 2022). "Ltbp2 is also robustly regulated in the failing RV in the SuHx model of PAH and in humans this gene has been identified as upregulated in myocardial samples from heart failure patients." (PMID 30213070, 2018).
Marfan syndrome (7 papers, 2013 to 2023). A disorder of the connective tissue. "Single-nucleotide polymorphisms in the LTBP2 gene are reported to be associated with various pathological conditions such as Marfan’s syndrome, mineral density variation and fracture risk, and skeletal and cardiovascular abnormalities." (PMID 23378721, 2013). "Phenotypic presentations in individuals of the Roma/Gypsy population who harbored homozygous mutations causing p.Arg299X in LTBP2 were reported to range from PCG with trabecular meshwork dysgenesis to Marfan syndrome-like zonular disease and late onset angle closure glaucoma." (PMID 23401661, 2013). "Thus, it is possible that LTBP-2 may also influence TGF-β bioavailability, supported by observations that some individuals with LTBP-2 mutations exhibit Marfan Syndrome-like characteristics linked to aberrant TGF-β upregulation." (PMID 28991210, 2017). "More recently, it was shown that LTBP2 mutations can also cause megalocornea, microspherophakia, and Weill-Marchesani syndrome (WMS; OMIM 277600) and promote Marfan syndrome (MFS; OMIM 154700) features." (PMID 23401661, 2013).
melanoma (7 papers, 2015 to 2021). A malignant, usually aggressive tumor composed of atypical, neoplastic melanocytes. "Monoubiquitinates H2AK119 at the promoter of LTBP2, thus regulates TGFβ signaling to induce melanoma." (PMID 32847129, 2020). "LTBP2 was also epigenetically silenced in chronic lymphocytic leukemia and melanoma." (PMID 30956730, 2019). "However, RNF2 also mono-ubiquitinates H2A at lysine K199 at the promoter of the latent-transforming growth factor beta-binding protein 2 (LTBP2), resulting in the activation of TGF-β signaling and invasion of melanoma cells." (PMID 33670160, 2021). "In melanoma, RNF2 has been shown to be oncogenic and prometastatic, and RNF2 can promote metastasis through the inhibition of LTBP2, while its oncogenic function does not require it catalytic activity and RNF2 promotes cell proliferation through direct transcriptional upregulation of CCND2." (PMID 28029659, 2017).
Weill-Marchesani syndrome (7 papers, 2013 to 2024). Weill-Marchesani syndrome (WMS) is a rare condition characterized by short stature, brachydactyly, joint stiffness, and characteristic eye abnormalities including microspherophakia, ectopia of the lens, severe myopia, and glaucoma. "The mutation of LTBP-2 has been linked to a form of Weill Marchesani syndrome (WMS), associated with cardiovascular defects in some patients." (PMID 35216218, 2022). "Involvement of LTBP2 mutations in hereditary systemic disorders, such as Marfan or Weill-Marchesani syndromes, has also been studied." (PMID 29751740, 2018). "In addition to involvement in PCG, pathogenic mutations in the LTBP2 gene have also been linked to Weill-Marchesani syndrome characterized by abnormalities of the lens of the eye, proportionate short stature, brachydactyly, and joint stiffness." (PMID 27409795, 2016). "Generalized ECM abnormalities resembling Marfan disease and Weill-Marchesani syndrome have been observed Further, LTBP2 has been identified as a potential candidate biomarker for fracture risk, death associated with pulmonary disease with acute dyspnea and adverse renal events in humans." (PMID 27149523, 2016).
lung fibrosis (5 papers, 2021 to 2025). "Consistently, in patients with COVID-19, LTBP2 levels are related to pulmonary fibrosis and are associated with disease severity." (PMID 36012423, 2022). "LTBP2 expression increases in response to myocardial stressors (e.g., pressure overload or isoproterenol) and has been associated with both cardiac and pulmonary fibrosis." (PMID 36012423, 2022). "These lung-specific features are consistent with the proposed value of LTBP2 as a marker for lung fibrosis." (PMID 40654695, 2025). "As recent single cell RNASeq analyses have improved resolution of mesenchymal cell subpopulations, we used two publicly available single cell RNA sequencing datasets to evaluate LTBP2 mRNA expression in pulmonary fibrosis and COPD18,19." (PMID 40654695, 2025). "The microfibril-binding protein LTBP2 is of specific interest as a clinically relevant biomarker predictive of disease progression in pulmonary fibrosis, and here we employ an LTBP2 KO mouse to evaluate the role of this protein in lung fibrosis models." (PMID 40654695, 2025). "In the current study, we characterized the expression pattern of LTBP2 and investigated for the first time its role in lung fibroblasts’ differentiation to myofibroblasts and lung fibrosis." (PMID 35002722, 2021). "Ltbp2 has been demonstrated to be secreted from lung myofibroblasts and could serve as a biomarker for idiopathic pulmonary fibrosis (IPF)." (PMID 35255963, 2022). "However, there has been very little research using LTBP2-knockout mice to assess lung fibrosis, and the exact function of LTBP2 in lung (myo) fibroblasts and PF remains unknown." (PMID 35002722, 2021). "Ltbp2 is involved in the TGFβ signaling pathway as it is required for the formation of the large latent complex (LLC) which binds latent TGFβ to the ECM and is secreted by myofibroblasts in pulmonary fibrosis." (PMID 37287453, 2023).
nasopharyngeal carcinoma (5 papers, 2013 to 2021). A carcinoma arising from the nasopharyngeal epithelium. "Previously, it was shown that promoter methylation is responsible for reduced expression of LTBP2 in nasopharyngeal carcinoma and ESCC." (PMID 23741501, 2013). "Low LTBP-2 expression levels were observed in nasopharyngeal carcinoma (NPC) cell lines and tumor samples from NPC patients." (PMID 24502434, 2013). "In nasopharyngeal carcinomas and ESCC LTBP2 expression is reduced and re-expression of LTBP2 in ESCC tumor cells suppresses neoplastic capacity in vitro and in vivo." (PMID 23741501, 2013). "LTBP2 is downregulated in ESCC and nasopharyngeal carcinomas." (PMID 23741501, 2013). "However, for LTBP2 it is known that hypermethylation of the promoter is responsible for the downregulation in ESCC and nasopharyngeal carcinomas." (PMID 23741501, 2013). "Both tumor suppressing and tumor promoting roles have been assigned to LTBP2: it is downregulated in nasopharyngeal carcinoma (NPC) and esophageal squamous cell carcinoma (ESCC), while it is upregulated in cervical, liver and ovarian cancers, and LTBP2 amplification has been reported in HNSCC." (PMID 27281608, 2016).
pancreatic cancer (5 papers, 2016 to 2022). "LTBP2 protein was upregulated in pancreatic cancer tissue samples and plasma samples from hepatocellular carcinoma (HCC) patients." (PMID 27281608, 2016). "In addition, some studies have found that high LTBP2 expression in tumor tissues of pancreatic cancer patients indicates a lower survival rate." (PMID 35968244, 2022). "The current review study identifies 22 IHC biomarkers as diagnostic tools for pancreatic cancer that embrace: Pentraxin-3, ENO1, REG4, POSTN, CA125, CA242, Galectin-1, Galectin-9, Maspin, pVHL, MUC1, MUC5AC, THBS2, LTBP2, CPA4, IMP3, CD13, Dkk1, KOC, S100P, Mesothelin, PAM4." (PMID 34988027, 2021). "Patients with high LTBP2 expression had poorer survival in pancreatic carcinoma." (PMID 30956730, 2019).
primary open angle glaucoma (5 papers, 2011 to 2024). "For example, open angle glaucoma presentations are associated with mutations of fibrillin-1, ADAMTS10 (a disintegrin and metalloproteinase with thrombospondin motifs-10) and LTBP2 (latent transforming growth factor β binding protein-2) that are different proteins involved in regulating microfibrils." (PMID 38347040, 2024).
cervical carcinoma (4 papers, 2016 to 2024). A carcinoma arising from either the exocervical squamous epithelium or the endocervical glandular epithelium. "LTBP2 was upregulated in cervical cancer cells and associated with clinical stage, tumor size, depth of stromal invasion and lymph node metastasis." (PMID 27281608, 2016). "LTBP2 is overexpressed in carcinomas of the uterine cervix, stomach, colon, pancreas, or HNSCCs, where the intensity of LTBP2 expression is inversely related to patients’ survival." (PMID 39201614, 2024). "The genes which were being termed as an essential marker for significant prognosis of cervical cancer were ADRA1D, LTBP2 whereas KLC2 protein-protein was termed for poor prognosis in early NsCLC patients." (PMID 35057823, 2022).
head and neck squamous cell carcinoma (4 papers, 2016 to 2022). A squamous cell carcinoma that arises from any of the following anatomic sites: lip and oral cavity, nasal cavity, paranasal sinuses, pharynx, larynx, and salivary glands. "For example, LTBP2 was found to be highly expressed in head and neck squamous cell carcinoma and significantly associated with lymph node metastasis and pTNM stage." (PMID 35968244, 2022). "On the other side, LTBP2 was upregulated in head and neck squamous cell carcinoma and was significantly related to lymph node metastasis and pTNM stage." (PMID 30956730, 2019). "In this study, we determined the expression levels of LTBP2 mRNA and protein in head and neck squamous cell carcinoma (HNSCC) tissues and adjacent normal tissues by quantitative reverse transcription PCR (qRT-PCR) and tissue microarray immunohistochemistry analysis (TMA-IHC) respectively." (PMID 27281608, 2016).
lung carcinoma (4 papers, 2019 to 2021). "In lung cancer, hypoxia induces BRG1 to regulate the proliferation and migration of lung cancer cells by activating cyclin B1 and LTBP2, whereas loss of BRG1 via siRNA treatment decreases hypoxia-induced migration and proliferation." (PMID 32354028, 2020). "They reported that SMARCA4 interacted with Sp1 to activate LTBP2 transcription, thus promoting lung cancer progression." (PMID 33853662, 2021). "BRG1 is pivotal for the expression of cyclin B1 and latent TGF binding protein 2 (LTBP2), the upregulation of which is correlated with malignant lung cancer growth." (PMID 32354028, 2020). "BRG1 depletion or inhibition was paralleled by down-regulation of cyclin B1 (CCNB1) and latent TGF-β binding protein 2 (LTBP2) in lung cancer cells." (PMID 31695026, 2019). "We report here that BRG1 recruits KDM3A to activate CCNB1 and LTBP2 transcription in lung cancer cells." (PMID 31695026, 2019). "It would be of great interest to determine whether this BRG1-KDM3A interplay extends beyond the regulation of CCNB1 and LTBP2 transcription and how it contributes to lung cancer oncogenesis in vivo." (PMID 31695026, 2019). "Here we present evidence to show that expression levels of BRG1, a chromatin remodeling protein, are elevated in human lung cancers as they become more aggressive paralleling the up-regulation of genes involved in cell proliferation (CCNB1) and migration (LTBP2)." (PMID 31695026, 2019).
Alzheimer disease (3 papers, 2023 to 2025). A progressive, neurodegenerative disease characterized by loss of function and death of nerve cells in several areas of the brain leading to loss of cognitive function such as memory and language. "Thus, in the analysis of the Mayo RNA-Seq dataset for Alzheimer’s disease, four of the DV genes detected in the control vs. AD comparison that have the largest estimated SD ratio above 1 are LTBP2, SLPI, C2orf40, and SLC47A1." (PMID 37790621, 2023).
colon cancer (3 papers, 2016 to 2018). "Prominent among those proteins was latent-transforming growth factor β-binding protein 2 (LTBP2)—an indicator of TGFβ signaling that has been previously identified as a product of CRC-associated fibroblasts obtained from a spontaneous mouse colon cancer model." (PMID 29176937, 2017). "Comparative proteomic analysis of murine CAFs isolated from sporadic colon cancer with their matched normal fibroblasts revealed upregulation of latent transforming growth factor beta binding protein 2 (LTBP2), farnesyl diphosphate synthase (FDPS), and cadherin 11 (CDH11) in CAFs." (PMID 29280568, 2018). "In colon cancer, LTBP2 was upregulated in tumor stromal cells, but not in cancer epithelial cells." (PMID 27281608, 2016).
colorectal cancer (3 papers, 2019 to 2025). A primary or metastatic malignant neoplasm that affects the colon or rectum. "A recent report demonstrated that LTBP2 was involved in the signaling pathway of the mesenchymal subtype in colorectal cancer." (PMID 30956730, 2019). "Our data suggested that LTBP2 may act as an oncogene in the development of colorectal cancer and have important significance in predicting CRC prognosis." (PMID 30956730, 2019). "High LTBP2 expression predicts a poor outcome for CRC patients and could be considered as a novel biomarker and potential therapeutic target for the high-risk CMS4 subtype of colorectal cancer." (PMID 30956730, 2019). "In conclusion, our study demonstrates that high LTBP2 expression correlates with inferior survival in patients with CRC and plays a critical role in the progression of colorectal cancer." (PMID 30956730, 2019).
esophageal squamous cell carcinoma (3 papers, 2015 to 2020). Esophageal squamous cell carcinoma (ESCC) is a type of esophageal carcinoma (EC) that can affect any part of the esophagus, but is usually located in the upper or middle third. "In contrast, LTBP2 is downregulated and performs a tumor-suppressive function in esophageal squamous cell carcinoma and nasopharyngeal carcinoma." (PMID 32826876, 2020).
exfoliation syndrome (3 papers, 2013 to 2024). An autosomal dominant disorder caused by mutations in the LOXL1 gene, encoding lysyl oxidase homolog 1. "Two studies reported LTBP1 and LTBP2 upregulation in the anterior segment of human tissues with pseudoexfoliation syndrome." (PMID 38928268, 2024). "Mutations in LTBP2, which binds to fibrillin-containing microfibrils, cause not only PCG, but also POAG and pseudoexfoliation glaucoma." (PMID 27484908, 2016).
glioma (3 papers, 2009 to 2024). A benign or malignant brain and spinal cord tumor that arises from glial cells (astrocytes, oligodendrocytes, ependymal cells). "While mutations in EFEMP2, ADAM10, SERPINH1, ADAM15, GAS6 and TNXB were detected only in patients with glioma grade 3, mutations in LTBP2, DCN, CRELD1 and HAPLN3 were observed only in patients with glioma grade 4, GBM." (PMID 38272115, 2024).
lymph node metastasis (3 papers, 2016 to 2022). "High LTBP2 protein expression was significantly associated with the presence of lymph node metastasis (P = 0.004) and higher stage (pTNM stage III–IV, P = 0.002)." (PMID 27281608, 2016). "High LTBP2 protein level was associated with lymph node metastasis and higher pTNM stages." (PMID 27281608, 2016). "In multivariate analysis, high LTBP2 expression (HR, 3.904, 95% CI: 2.253–6.766; P < 0.001) and presence of lymph node metastasis (HR, 2.701, 95% CI: 1.243–5.867; P = 0.012) remain significantly associated with poor overall survival." (PMID 27281608, 2016).
oral squamous cell carcinoma (3 papers, 2022 to 2024). "Moreover, reports have highlighted that EMT can be initiated by the circEPSTI1/miR-942-5p/LTBP2 axis in oral squamous cell carcinoma (OSCC) cells." (PMID 38706897, 2024). "The circEPSTI1/mir-942-5p/LTBP2 regulatory axis was also identified to affect the proliferation and invasion of oral squamous cell carcinoma (OSCC) cells through the acceleration of epithelial-mesenchymal transition (EMT) and phosphorylation of PI3K/Akt/mTOR signaling pathway." (PMID 35255963, 2022).
thyroid cancer (3 papers, 2017 to 2019). "It is noteworthy that a very recent paper has shown that LTBP-2 knockdown inhibits invasion and tumorigenesis in thyroid cancer cells and this involves the PI3K/Akt signalling pathway." (PMID 28991210, 2017). "A mechanism study displayed that knockdown of LTBP2 inhibited the proliferation, migration, invasion, and epithelial-to-mesenchymal transition (EMT) of a phenotype of thyroid carcinoma cells." (PMID 30956730, 2019).